ERBB2 (erb-b2 receptor tyrosine kinase 2)
Diseases named in the same sentence as ERBB2 in open-access papers (continued):
Sharing a sentence is not in itself a finding about the gene and the disease.
gastric cancer (continued). "Growing evidence supports the use of small-molecule MET or ERBB2 inhibitors in gastric cancer, particularly in molecularly defined subgroups with receptor overexpression." (PMID 40723172, 2025). "Epidermal growth factor receptor 2 (ERBB2/HER2) is a critical biomarker in gastric cancer management, but the clinical implications of specific ERBB2 mutations remain poorly characterized." (PMID 40699829, 2025). "The dual luciferase reporter system test and RT-qPCR results demonstrated that ERBB2 was the miR-497-5p target gene in gastric cancer cells." (PMID 38911367, 2024). "We performed rescue studies to investigate the role of miR-497-5p in the biological activity of gastric cancer cells, as ERBB2 is a potential target of this miRNA." (PMID 38911367, 2024). "Analysis of ERBB2 expression characteristics in gastric cancer tissues revealed that ERBB2 expression levels were considerably higher than in normal tissues (P < 0.05)." (PMID 38911367, 2024). "Despite success in breast and gastric cancers, clinical trials with anti-ERBB2 treatments have shown limited efficacy in bladder cancer." (PMID 39410541, 2024). "Using GCAP, we identified two ERBB2 amplified gastric cancers with ecDNA+ status from our deposited clinical tumor WES data." (PMID 38373991, 2024). "When compared to the miR-497-5p mimic group, the RT-qPCR experiment demonstrated that the miR-497-5p mimic significantly reduced ERBB2 expression in gastric cancer cells (P < 0.01)." (PMID 38911367, 2024). "The gastric cancer genome is characterized by focal amplification of oncogenes, including receptor tyrosine kinases, such as ERBB2 (HER2), EGFR, ERBB3, VEGF-A, KRAS/NRAS, MET, JAK2, and PD-L1/PD-L2." (PMID 38733489, 2024). "While no agents targeting amplified genes are currently licensed for HGSOC, the success of HER2 targeting agents in treating ERBB2-amplified breast and gastric cancers demonstrates the scope for translational research." (PMID 36804485, 2023). "Using ERBB2 as a prognostic indicator for breast and gastric cancers, the most extensively studied cancers, several studies have demonstrated that tumor recurrence, metastasis, and poor overall survival are associated with high serum ERBB2 levels." (PMID 37174100, 2023). "ERBB2 (also known as Her2/neu) is an oncogene that is overexpressed in many types of cancers (e.g., breast, ovarian, and gastric cancers), and its activation correlates with a poor prognosis." (PMID 37109525, 2023). "Our present study used CISH analysis, which is a well‐established and clinically adopted technique to interrogate genetic amplification such as evaluation of ERBB2 amplification in breast and gastric cancer." (PMID 36572991, 2023). "The authors found a subgroup of cells between the metastatic group and primary group and discovered some gastric cancer lymph node metastasis marker genes (ERBB2, CLDN11, and CDK12), as well as potential gastric cancer evolution-driving genes (FOS and JUN)." (PMID 37612741, 2023). "GSDMB is frequently co-expressed with HER2/Erbb2 oncogene in breast and gastric carcinomas, where GSDMB over-expression promotes tumorigenesis, invasion, metastasis, and resistance to therapy." (PMID 36899106, 2023). "FISH is an established and straight-forward applicable technique in clinical routine diagnostics for the detection of amplifications with the potential of prognostic or predictive biomarkers in various cancer entities, e.g., ERBB2 in breast and gastric cancer." (PMID 35668118, 2022). "Somatic ERBB2 SNVs/indels occurred most common in bladder/urinary tract cancer (13/177, 7.3%), intestine cancer (11/179, 6.1%), stomach cancer (41/998, 4.1%), endometrium cancer (5/152, 3.3%), and lung cancer (125/4,624, 2.7%)." (PMID 35911441, 2022).
gastric cancer (continued). "As recently reported, liquid biopsy-identified mutation of PIK3CA/HER2/NF1, increased ERBB2 copy number as well as upregulation of ERBB-family ligands, can induce Trastuzumab resistance in gastric cancer." (PMID 36463209, 2022). "The gastric cancer group with N0 or N1 metastasis formed clusters with high expressions of ERBB2 mRNA and MET mRNA." (PMID 35650563, 2022). "Gastric cancer exhibits alterations in the ErbB receptor family and ErbB-related signalling pathways; in particular, the expression level of ErbB2 is increased in gastric cancer, and ErbB2 targeted therapies for gastric cancer have proved highly beneficial." (PMID 36299773, 2022). "The reason for the obvious increase in PD-L1 in ERBB2-overexpressing gastric cancer is that STAT3 in the ERBB2 pathway and the ERBB2d16 pathway can directly increase the expression of PD-L1 in tumor tissue, as reported." (PMID 35463314, 2022). "Gastric cancer targeted therapies have been notorious for their failure in late-stage trials, with only two (targeting ERBB2 and VEGFR2) currently approved by the FDA." (PMID 36970058, 2022). "After screening for oncogenes or suppressor genes, KIT, KRAS, and ERBB2 were significantly higher in gastric cancer ECs." (PMID 35755820, 2022). "On the other hand, a recent glycosylation profiling of the ErbB2 ectodomain, an oncogenic cell surface receptor tyrosine kinase, revealed a site-specific glycosylation profile in gastric cancer cells." (PMID 35163546, 2022). "By specifically targeting the ErbB2 N-glycosylation sites in the trastuzumab-binding domain, ST6Gal1-mediated aberrant α-2,6-sialylation actively tunes the resistance of ErbB2-driven gastric cancer cells to trastuzumab." (PMID 35163546, 2022). "A key member of the EGFR family, ERBB2, has been elucidated in regulating development of breast and gastric cancers." (PMID 35360837, 2022). "The expression or amplification of ERBB-2 is correlated with various cancers, including lung, breast, ovarian, and gastric cancers." (PMID 35574028, 2022). "5, 5, 3, and 2 mutations of KRAS, PIK3CA, ERBB2 and CTNNB1 were observed in 4, 4, 3, and 2 gastric cancers, respectively (5, 3, 3, and 2 hotspot mutations, respectively)." (PMID 34873204, 2021). "In gastric cancer, which shows a frequency similar to that in this study, trastuzumab targeted at ERBB2 and ramucirumab targeted at VEGFR have been observed to be effective for treatment." (PMID 34316332, 2021). "The treatment of EGFR and HER2 overexpressing gastric cancer cells with Afatinib (a pan-ErbB2 family TKI) and lapatinib (EGFR, ErbB2 inhibitor) reduced PD-L1 expression levels." (PMID 33807608, 2021). "Trastuzumab (Herceptin®) is a humanized recombinant monoclonal antibody (mAb) of the immunoglobulin G1 type, approved by the FDA for treatment of breast and gastric cancer with overexpression of ErbB2 (HER2)." (PMID 33810567, 2021). "The clinical performance of the therapeutic monoclonal antibody trastuzumab in the treatment of ErbB2-positive unresectable gastric cancer (GC) is severely hampered by the emergence of molecular resistance." (PMID 33947960, 2021). "A previous study showed that an ERBB2 inhibitor combined with apatinib was effective against HER2-positive gastric cancer and acquired resistance against the ERBB2 inhibitor." (PMID 34459788, 2021). "In fact, combination of ERBB2 antagonist or RARA agonist was reported to be effective synergistic regimens for ERBB2 positive gastric cancer." (PMID 33897415, 2021). "As for gene amplifications, gastric cancers with current and past infection also had similar frequencies of ERBB2 amplification (9% and 3%; p = 0.398) and KRAS amplification (2% and 3%; p = 1.000)." (PMID 34873204, 2021).
gastric cancer (continued). "Approximately 12–15% of gastric cancers (GCs) are human epidermal growth factor receptor-2 (HER2)-positive (HER2 immunohistochemistry 3 + or 2 + /in situ hybridization + [ERBB2/CEP17 ≥ 2.0])." (PMID 33997928, 2021). "ERBB2 was most frequently amplified (6 of the 90 gastric cancers, 7%), and KRAS (2 cancers, 2%), PIK3CA (1 cancer, 1%), and MET (1 cancer, 1%) followed." (PMID 34873204, 2021). "ERBB2) has been identified as a key molecular target for gastric cancer treatment even since before the era of comprehensive molecular characterization of gastric cancer began." (PMID 34680363, 2021). "For instance, ctDNA analysis has been successfully used to detect resistant mutations in genes such as EGFR, ERBB2, PIK3CA, and RAS, in various cancers including NSCLC, CRC, and gastric cancer." (PMID 33673461, 2021). "Among the 90 gastric cancers, 10 cancers had gene amplification of one of ERBB2, KRAS, PIK3CA, and MET." (PMID 34873204, 2021). "Oxaliplatin and trastuzumab have a synergistic antitumor effect in gastric cancer cells with Erb-B2 receptor tyrosine kinase 2 (ERBB2)." (PMID 34357103, 2021). "HER2 (human epidermal growth factor receptor 2 (ERBB2)) amplification is found in 10-15% of gastric cancer patients, and trastuzumab is a monoclonal antibody drug that directly targets HER2." (PMID 33623790, 2021). "For example, overexpression and amplification of ERBB2 had been a predictive marker for anti-HER2 therapy in gastric cancer." (PMID 35252219, 2021). "Amplifications of ERBB2 are found in 22% of gastric cancer patients and patients carrying such a amplification can be successfully treated with trastuzumab." (PMID 33223522, 2021). "ErbB2 expression was evaluated by immunohistochemistry in a retrospective series of 173 stage I–IV gastric carcinomas." (PMID 33947960, 2021). "The role of miR-125a as a regulator of ErbB2 in both breast and gastric cancer cells has already been established." (PMID 32185126, 2020). "A similar interaction was observed in ErbB2-highly expressing gastric cancer cells, as miR-125a-5p was shown to repress ErbB2 expression and in addition, to be inversely correlated with expression of ErbB2 in clinical samples." (PMID 32185126, 2020). "Beyond breast and gastric cancer, there is a need to develop new treatment options for patients with ERBB2 amplified or ERBB2-mutant solid tumours, as HER2-expressing lung, bladder, colorectal and endometrial cancers." (PMID 32641355, 2020). "ERBB2-related pathways can help us finding sensitive molecules and potential combined therapeutic targets of ERBB2-targeted therapy for gastric cancer." (PMID 32883271, 2020). "In particular, we identified high ERBB2 mRNA in a patient with HER2+ advanced gastric cancer who achieved a long-lasting partial response to T-DM1." (PMID 32674482, 2020). "A translational study evaluating gastric cancer samples of the GATSBY trial demonstrated more benefit to T-DM1 in terms of PFS in patients with tumors with higher ERBB2 mRNA levels." (PMID 32674482, 2020). "Anti-ERBB2 antibodies (under the generic name trastuzmab) can be used to treat breast and gastric cancer." (PMID 33092526, 2020). "Human epidermal growth factor receptor 2 (HER-2), a tyrosine kinase receptor assigned to the family of epidermal growth factor receptor (EGFR), is a crucial gastric cancer therapeutic target encoded by the c-erbB2 proto-oncogene located on chromosome 17q212." (PMID 33173435, 2020). "Human epidermal growth factor receptor 2 (HER2), encoded by the ERBB2 gene, has been established as an important biomarker with both prognostic and therapeutic implications in breast and gastric cancers." (PMID 33375706, 2020).
gastric cancer (continued). "In the same manner, miR-125a-5p was able to reduce the expression of ErbB2 in human gastric cancer cells that highly express ErbB2 and to suppress the proliferation of the cells." (PMID 32185126, 2020). "Alterations in RTK activities, including EGFR, HER2 (ErbB2, EGFR2), and MET (HGFR), are associated with gastric cancer progression." (PMID 32005975, 2020). "In summary, GPAA1 expression was highly synergistic with ERBB2 expression, and this expression was correlated with the progression of gastric cancer and predicted unsatisfactory outcomes." (PMID 31118109, 2019). "For example, upregulation of RUNX1 led to the increased expression of SOS1 and phosphorylation of ErbB2/HER2, subsequently promoting the proliferation of gastric cancer cells." (PMID 31592165, 2019). "Kadcyla is made of trastuzumab conjugated via a non-cleavable linker to the microtubule disrupting agent emtansine and it is approved for the treatment of metastatic ErbB2-expressing breast and gastric cancer." (PMID 32039017, 2019). "Overexpression/amplification of the human epidermal growth factor receptor 2 (HER2)/avian erythroblastosis oncogene B2 (ERBB2) occurs in 15–25% of invasive breast, ovarian and gastric cancers and is associated with poor prognosis." (PMID 31086176, 2019). "Our study showed the positive rate of HER2/c-erbB-2 in gastric cancer was 32.8%, which is slightly lower than that of Yan." (PMID 33817143, 2019). "Li showed that upregulation of circular RNA circ-ERBB2 predicts unfavorable prognosis and facilitates the progression of gastric cancer via miR-503/CACUL1 signaling." (PMID 31249473, 2019). "It was first approved by FDA in 1998 and ever since employed widely worldwide for the treatment of primary and metastatic ErbB2+ breast and gastric cancer." (PMID 32039017, 2019). "HER2/c-erbB-2 protein mainly expressed in the cell membrane of gastric cancer cells with brownish yellow particles." (PMID 33817143, 2019). "Then, the Kaplan-Meier method and log-rank test were used to evaluate the effects of GPAA1 and ERBB2 alone and in combination on the survival rate of gastric cancer patients." (PMID 31118109, 2019). "ERBB2 amplification is especially important in breast- and gastric carcinomas and is therapeutically targetable using e.g. the tyrosine-kinase inhibitor trastuzumab." (PMID 30717682, 2019). "Taken together, our work identified a novel interaction of RUNX1 and the ErbB2/HER2 signaling pathway in gastric cancer, which can potentially be exploited in the management of this malignancy." (PMID 29686309, 2018). "Taken together, these data collectively suggested that RUNX1 positively regulates the ErbB2/HER2 signaling pathway through directly transactivating SOS1 expression in the gastric cancer cells." (PMID 29686309, 2018). "Exploring ERBB2-related pathways will help us finding sensitive molecules and potential combined therapeutic targets of ERBB2-targeted therapy for ERBB2+ gastric cancer (GC)." (PMID 30123134, 2018). "Knockdown of RUNX1 led to the decreased expression of SOS1 as well as dephosphorylation of ErbB2/HER2, subsequently suppressed the proliferation of gastric cancer cells." (PMID 29686309, 2018). "The fact that our approach also identifies the well-known trans-cancer efficacy of ERBB2/Her2 inhibition in breast and gastric cancer supports the potential clinical value of our predictions." (PMID 30442178, 2018). "To confirm our finding, we performed immunoblot experiment and validated that RUNX1-silencing indeed dephosphorylated ErbB2/HER2 in the gastric cancer cells." (PMID 29686309, 2018). "Overexpression of RTKs has been found in a variety of human cancers: EGFR in GBM, lung, esophageal and thyroid cancer; HER2/ErbB2 in lung, bladder, breast and gastric cancer; and MET in lung and gastric cancer." (PMID 29455648, 2018). "Trastuzumab, a monoclonal antibody that acts on the HER2/neu (erbB2) receptor, is currently used to treat HER2-positive advanced gastric cancer." (PMID 29849601, 2018).
gastric cancer (continued). "Herein we report that RUNX1 regulates the ErbB2/HER2 signaling pathway in gastric cancer cells through transactivating SOS1 expression, rendering itself an ideal target in anti-tumor strategy toward this cancer." (PMID 29686309, 2018). "We herein revealed that RUNX1 potentially participates in the maintenance of gastric cancer cells through enhancing the activity of the ErbB2/HER2 signaling pathway by directly transactivating SOS1 expression." (PMID 29686309, 2018). "In conclusion, our work identified a novel role of RUNX1 in the ErbB2/HER2 signaling pathway in gastric cancer cells." (PMID 29686309, 2018). "Together with the results obtained in the RUNX1 knockdown experiments, we were convinced that RUNX1 controls the ErbB2/HER2 signaling cascade through modulating SOS1 expression in gastric cancer cells." (PMID 29686309, 2018). "Previous studies indicate that ganetespib has anti-proliferative effects on ErbB2+ gastric cancer cells." (PMID 29717218, 2018). "In this report, we show evidence that RUNX1 plays a key role in the maintenance of gastric cancer cells by regulating the ErbB2/HER2 signaling pathway." (PMID 29686309, 2018). "Up-regulation of the ErbB2/HER2 signaling pathway is frequently-encountered in gastric cancer and contributes to the maintenance of these cancer cells." (PMID 29686309, 2018). "Amplification/overexpression of the ERBB2 gene in esophageal or EGJ ADC were more frequent than that observed in gastric cancer, accounting for 24%-32%." (PMID 33748520, 2018). "Human epidermal growth factor receptor-2 (HER-2), a transmembrane tyrosine kinase receptor belonging to the family of epidermal growth factor receptor (EGFR), is an important gastric cancer target encoded by the ErbB2 gene located on chromosome 17q21." (PMID 29986466, 2018). "A targeted therapy is recommended in case of ERBB2 alteration for breast and gastric carcinomas, but miscellaneous other tumor types are ERBB2-altered at low prevalence." (PMID 29515767, 2018). "Together, these data strongly suggested that ERBB2 was inseparable to induce Rac1 activation and participated in the migration and invasion of gastric cancer cells." (PMID 28099468, 2017). "The authors also analyzed the somatic mutations of EGFR, ERBB2, PIK3CA, KRAS, and BRAF genes in these 12 samples harboring ERBB4 mutations and detected a KRAS mutation in 1 gastric cancer sample." (PMID 29371993, 2017). "We further advocate that miR-1296-5p can inhibit cell migration by repressing ERBB2 expression and Rac1 activation in gastric cancer cells." (PMID 28099468, 2017). "Here, we suggest for the first time that the miR-1296-5p level is inversely correlated with ERBB2 expression in gastric cancers, and miR-1296-5p repressed ERBB2 expression in gastric cancer cells." (PMID 28099468, 2017). "This experiment investigated the suppressive role of miR-3622b-5p in ERBB2-positive breast and gastric cancers." (PMID 28160563, 2017). "In this article, our experiment verifies the inhibitive role of miR-1296-5p in the migration and invasion of ERBB2-postive gastric cancer cells that is achieved by suppressing ERBB2 expression and Rac1 activation." (PMID 28099468, 2017). "Although trastuzumab is an approved therapy for gastric cancers with ERBB2 overexpression or amplification, clinical response rates and improvements in median overall survival are short-lived and modest." (PMID 29872697, 2017). "The luciferase activity of ERBB2 3'-untranslated region-based reporters constructed in SNU-216 and NUGC-4 gastric cancer cells suggested that ERBB2 was the target gene of miR-1296-5p." (PMID 28099468, 2017). "MiR-1296-5p was down-regulated in ERBB2-positive gastric cancer tissues compared with ERBB2-negative gastric cancer tissues." (PMID 28099468, 2017).